GLYCTK (glycerate kinase)
Synonyms: HBEBP4; HBEBP2; HBeAgBP4A
Tractability: PROTAC: ubiquitination databases record sites on it; its protein half-life has been measured.
Gene: Protein-coding gene on chromosome 3 (52,286,945 to 52,295,273, forward strand). Ensembl gene ENSG00000168237.
Subcellular location: Mitochondrion matrix (Isoform 1)
Subcellular location (Human Protein Atlas): Cytosol; Golgi apparatus; Rods & Rings
Pathways (Reactome):
Metabolism: Fructose catabolism
Gene Ontology:
Molecular function: glycerate kinase activity; protein binding
Biological process: protein phosphorylation; fructose catabolic process
Cellular component: cytoplasm; cytosol; mitochondrion; mitochondrial matrix
Genetic constraint (gnomAD): Loss-of-function variants: 28 observed, 29.54 expected, observed/expected ratio (o/e) 0.95, 90% interval 0.7 to 1.3. The upper end of that interval is the gene's LOEUF score, 1.3, which puts it in group 5 of 6, group 1 being the genes least tolerant of losing a copy. Missense variants: 684 observed, 710.35 expected, observed/expected ratio (o/e) 0.96, 90% interval 0.9 to 1.03. Synonymous variants: 320 observed, 309.19 expected, observed/expected ratio (o/e) 1.03, 90% interval 0.94 to 1.13.
Gene-disease validity (ClinGen):
ClinGen rates the evidence that GLYCTK causes each of these diseases.
D-glyceric aciduria (autosomal recessive): Moderate. A metabolic disorder characterized by D-glyceric acid excretion.
Homologues: Orthologues: chimpanzee GLYCTK (99% identical), macaque GLYCTK (97% identical), rabbit GLYCTK (89% identical), pig GLYCTK (86% identical), mouse Glyctk (84% identical), rat Glyctk (84% identical), guinea pig GLYCTK (83% identical), dog GLYCTK (80% identical), zebrafish glyctk (52% identical), Drosophila melanogaster CG9886 (35% identical), Caenorhabditis elegans C13B9.2 (32% identical), tropical clawed frog glyctk (26% identical).
Diseases named in the same sentence as GLYCTK in open-access papers:
GLYCTK is named in the same sentence as 9 diseases in open-access papers, as found by Europe PMC text mining. Sharing a sentence is not in itself a finding about the gene and the disease. The quoted sentences say what the papers report.
colorectal cancer (2 papers, 2019 to 2026). A primary or metastatic malignant neoplasm that affects the colon or rectum. "To assess the contribution of these enzymes to the formation of phosphoglycolate, we transduced the HCT116 colorectal cancer cell line with lentiviral constructs driving the expression of shRNAs specific for PKM (coding for pyruvate kinases M1 and M2) or GLYCTK (coding for glycerate kinase)." (PMID 30670572, 2019).
attention deficit-hyperactivity disorder (1 paper, 2018). A disorder characterized by a marked pattern of inattention and/or hyperactivity-impulsivity that is inconsistent with developmental level and clearly interferes with functioning in at least two settings (e.g. at home and at school). "The remaining genes, such as GLYCTK, DRD5, NPHP3, and FANCI, were well-characterized pathogenic genes for some other rare diseases with recessive mode of inheritance or multi-gene diseases, such as D-glyceric aciduria, attention deficit-hyperactivity disorder, Meckel syndrome, and Fanconi Anemia." (PMID 30693022, 2018).
tumor (1 paper, 2026). "The immune infiltration analyses suggested that GLYCTK is associated with an immune-cold tumor microenvironment, whereas functional assays indicated that GLYCTK promotes proliferation, migration and invasion in CRC cells." (PMID 42112339, 2026).
GLYCTK also shares sentences with these, for which no sentence is quoted: D-glyceric aciduria (1 paper); Fanconi anemia (1); Meckel syndrome (1); melanoma (1); ovarian serous cystadenocarcinoma (1); uterine carcinosarcoma (1).